CXCL13 (C-X-C motif chemokine ligand 13)
Diseases named in the same sentence as CXCL13 in open-access papers (continued):
Sharing a sentence is not in itself a finding about the gene and the disease.
periodontitis (10 papers, 2013 to 2025). An acute or chronic inflammatory process that affects the tissues that surround and support the teeth. "As mentioned, not only IL-6 levels but also CCL27 and CXCL13 high levels were previously associated with periodontitis." (PMID 35048045, 2021). "The number of CXCL13 cells is reportedly significantly higher in periodontitis, suggesting that this condition is associated with alveolar bone resorption." (PMID 24376796, 2013). "We identified CXCL13+ fibroblast subset potentially involved in immune response, which exhibited increased presence in periodontitis." (PMID 34566966, 2021). "In advanced human periodontitis, T and B/plasma cells predominate, for which CXCL13 and CCL19 expression from the ICAM1+ fibroblasts may be important as they are chemotactic for B and T cells, respectively." (PMID 39650645, 2024). "Also, the predominant subpopulation converted from OCN+ fibroblasts (Fibro_2) to CXCL13+ (Fibro_1) fibroblasts when the gingival tissue was infiltrated with inflammatory cells in periodontitis." (PMID 34566966, 2021). "The enrichment of TNFRSF21+ fibroblasts with high expression of CXCL1, CXCL2, CXCL5, CXCL6, CXCL13, and IL24 was detected in patients with periodontitis compared to healthy individuals." (PMID 35154475, 2022). "Previous studies have reported heterogeneity in gingival fibroblasts in periodontal tissues, with four subsets significantly altered in periodontitis: Fib 1.1 (CXCL1, CXCL2, CXCL13); Fib 1.2 (APCDD1, IGFBP2, MRPS6); Fib 1.3 (APOD, GSN, CFD); and Fib 1.4 (TIMP3, ASPN, COL11A1)." (PMID 40801798, 2025). "Similarly, keratinocytes in periodontitis patients show increased expression of CXCL1, CXCL3, CXCL8, CXCL13, and CCL20, suggesting that chemokine expression in gingival fibroblasts and epithelial cells drives chronic periodontitis." (PMID 40565042, 2025). "In addition, it can act on endothelial cells via the CXCL1/ACKR1 and CXCL13/ACKR1 axes, and we hypothesized that this may promote endothelial cell angiogenesis, leading to gingival bleeding in periodontitis." (PMID 40370461, 2025).
cutaneous melanoma (9 papers, 2020 to 2024). A primary melanoma arising from atypical melanocytes in the skin. "Previous studies have shown that CXCL13 was expressed in cutaneous melanoma more than in normal tissue and was associated with better overall survival." (PMID 35141160, 2022). "These aspects of the CXCL13/CXCR5-associated immune axis are highlighted in this review, which focuses on cutaneous malignant melanoma." (PMID 36836910, 2023). "primarily identified five chemokine members (CCL4, CCL5, CXCL9, CXCL10, CXCL13) as relevant biomarkers in cutaneous melanoma tumorigenesis and progression." (PMID 36713580, 2022). "Specifically, we propose that the CXCR5/CXCL13-axis may represent an additional target for anti-PD-1 therapy in cutaneous melanoma, that is relevant for treatment outcome as well as a potential source of predictive therapeutic biomarkers." (PMID 36836910, 2023). "Patients with high expression of CXCL9, CXCL10, CXCL13, CCL4, and CCL5 in SKCM (Skin cutaneous melanoma) had better overall survival." (PMID 36341437, 2022). "In summary, this study mainly identified five chemokine members (CXCL9, CXCL10, CXCL13, CCL4, CCL5) associated with SKCM tumorigenesis, progression, prognosis and immune infiltrations, which might help us evaluate several immune-related targets for cutaneous melanoma therapy." (PMID 32508531, 2020).
meningitis (9 papers, 2017 to 2025). A disorder characterized by acute inflammation of the meninges of the brain and/or spinal cord. "Another two samples, one from a patient with herpes simplex 2 meningitis and one with meningitis due to Streptococcus pneumoniae, showed grey zone results with the ReaScan CXCL13, but high concentrations with recomBead CXCL13." (PMID 34626256, 2022). "It has been revealed that CXCL13 demonstrates a lower but still high performance in discriminating between meningitis and meningoencephalitis in comparison to the total lymphocyte and total cell count in the CFS." (PMID 34638953, 2021). "CSF CXCL13 test would be especially helpful in an emergency setting when children present with acute facial palsy or headache and meningitis." (PMID 28859668, 2017). "Our findings underscore this point by demonstrating that CSF levels of CXCL13 are below the proposed 162 pg/mL diagnostic cutoff in most patients with suspected LNB (median CXCL13 levels 1 pg/mL) and even in many patients with PFP/meningitis (median CXCL13 levels 53 pg/mL)." (PMID 35318928, 2022). "It has been observed that in meningoencephalitis, the concentration of CXCL13 in the CSF, as well as pleocytosis, and the CSF/serum ratio of specific anti-TBEV antibodies were higher in comparison to meningitis." (PMID 34638953, 2021).
renal cell carcinoma (9 papers, 2021 to 2025). "Lastly, through improvements in our ability to delineate subsets of tumor infiltrating T cells, we show that CXCL13-expressing CD8+ T cells tend to be more closely associated with tumor cells than their CXCL13-negative counterparts in data generated from renal cell carcinoma patient samples." (PMID 38712065, 2024). "CXCL13 has been shown to activate mTOR signaling pathway through its interaction with CXCR5 on renal cell carcinoma." (PMID 40599793, 2025). "The CXCL13 neutralizing antibody has been reported to be used in hyperalgesia, pancreatic ductal adenocarcinoma, and renal cell carcinoma." (PMID 38880863, 2024). "For example, it was shown that CXCL13-secreting M2 macrophages in the tumor microenvironment promote the proliferation, invasion, and migration of renal cell carcinoma tumor cells." (PMID 36217194, 2022). "Stimulation of CXCL13 may activate Akt pathway, suggesting an increase in M2 macrophage in renal cell carcinoma." (PMID 38149248, 2023). "Renal cell carcinoma, a typical immune-excluded tumor, is considered to lack the expression of some chemokines related to T cell recruitment, such as CXCL9, CXCL10, CXCL11, CXCL13, CX3CL1, CCL2, and CCL5, in its TME, but the specific mechanisms underlying this lack of chemokines remain unclear." (PMID 36397015, 2022).
Sepsis (9 papers, 2019 to 2025). Sepsis is defined as life-threatening organ dysfunction caused by a dysregulated host response to infection. "Of note, both VEGF-A and CXCL13 are known inducer of BBB disruption while CXCR5, the receptor for CXCL13, is linked to hippocampal neuroinflammation and cognitive impairment in animal models of sepsis and surgery." (PMID 41219650, 2025). "Several of the top regulated genes that are shared between CLP-induced and LPS-induced septic hearts, such as Cxcl13, Lcn2, and Serpina3m, have been implicated in the development of endothelial hyperpermeability and human sepsis." (PMID 37510271, 2023). "Along this line of thinking, we observed a positive correlation between postoperative CXCL13 levels and the leucocyte count, which is in good agreement with data on elevated CXCL13 levels in patients with systemic inflammation or sepsis." (PMID 36077611, 2022). "In the present study, we confirm the elevation of CXC chemokine ligand 13 (CXCL13) in sepsis patients." (PMID 32500306, 2020). "ELISA analysis showed that CXCL13 was significantly elevated in the serum of patients with sepsis (n = 40) compared with age-matched healthy control." (PMID 32500306, 2020). "In summary, serum concentrations of CXCL13 were elevated in patients with sepsis patients and in the sepsis mouse model." (PMID 32500306, 2020). "It has been reported that CXCL13 levels in the serum were significantly elevated in patients with sepsis compared with that in healthy controls." (PMID 32500306, 2020). "More importantly, pretreatment with CXCL13-neutralizing antibody significantly improved the survival rate of LPS-induced sepsis mice." (PMID 32500306, 2020). "Therapeutically targeting CXCL13, thus, may prove beneficial for reducing endothelial permeability and could be an effective treatment option against sepsis." (PMID 32500306, 2020). "To test the effect of CXCL13 in vivo, we established an LPS-induced sepsis mouse model." (PMID 32500306, 2020). "Here, we show that CXCL13 concentration is elevated in the serum of patients with sepsis." (PMID 32500306, 2020). "Elevated CXCL13 was also observed in the LPS-induced sepsis mouse model and LPS-treated HUVECs." (PMID 32500306, 2020). "Our in vitro and in vivo data, therefore, suggest that therapeutically targeting CXCL13 may be beneficial for the clinical treatment of sepsis." (PMID 32500306, 2020). "In the current study, we aimed to investigate the role of CXCL13 in LPS-induced permeability of HUVECs, examine the phosphorylation of p38 during this process, and test the effects of a CXCL13-neutralizing antibody on an LPS-induced sepsis mouse model." (PMID 32500306, 2020). "Moreover, the CXCL13-neutralizing antibody significantly increased the survival rate of LPS-induced sepsis mice." (PMID 32500306, 2020). "CXCL13 level was increased in the serum of patients with sepsis, and CXCL13 also acts via p38MAPK signaling to drive LPS-induced hyperpermeability of the endothelium in human umbilical vein endothelial cells, suggesting that targeting CXCL13 may alleviate sepsis." (PMID 34711216, 2021). "The elevation of CXCL13 in sepsis may derived from multiple cell types." (PMID 32500306, 2020). "Collectively, our results show that CXCL13 plays a key role in LPS-induced endothelium hyperpermeability via regulating p38 signaling and suggests that therapeutically targeting CXCL13 may be beneficial for the treatment of sepsis." (PMID 32500306, 2020). "Several chemokines have been identified as biomarkers for sepsis, such as CXCL8, CXCL13, CCL2, and CCL8." (PMID 32500306, 2020).
serous ovarian cancer (9 papers, 2020 to 2025). "Further, we have constructed an immune-related risk model based on TAP1 and CXCL13 for the first time to predict the prognostic response of advanced serous ovarian cancer." (PMID 34631788, 2021). "In high-grade serous ovarian cancer, elevated CXCL13 expression correlates with increased infiltration and activation of CXCR5+ CD8+ T cells within the TME." (PMID 40352278, 2025). "Intraperitoneal injection of CXCL13 also enhanced the anti-tumor effect of anti-PD-1 treatment depending on the infiltration of CXCR5+ CD8+ T cells in high-grade serous ovarian cancer mice." (PMID 38690273, 2024). "RNA ISH staining of high-grade serous ovarian cancer revealed that CXCL13 was predominantly secreted by CD4+ T cells in immature state, and FDC in mature state." (PMID 38690273, 2024). "In high-grade serous ovarian cancer, CXCL13 increases infiltration of TILs and is helpful to enhance efficacy of ICT." (PMID 37488535, 2023). "A large study of high-grade serous ovarian cancer found CXCL13 enhanced immune efficacy in combination with PDL1 by promoting the expansion and activation of CXCR5 + CD8 + T cells." (PMID 36704336, 2022). "In this study, we screened the immune-related genes of serous ovarian cancer from a different perspective and discovered the importance of TAP1 and CXCL13 as independent prognostic and predictive markers for serous ovarian cancer." (PMID 34631788, 2021). "The combined assessment of CXCL13, CXCR5, and CD8+ T cells serve as an independent predictor of survival in high-grade serous ovarian cancer." (PMID 40352278, 2025).
Stroke (9 papers, 2013 to 2025). Sudden impairment of blood flow to a part of the brain due to occlusion or rupture of an artery to the brain. "CXCL13 also seems to play an important role in the infiltration of T follicular helper cells into the ischemic tissue after stroke." (PMID 37765263, 2023). "Previously reports have identified that CXCL13 is expressed on ischemic blood vessels within the brain after stroke." (PMID 35624463, 2022). "A different experimental study analyzing the transcriptome of the ischemic penumbra found that Cxcl13 mRNA is still upregulated as late as 8 weeks after stroke." (PMID 33058417, 2020). "It has been shown that Cxcl13 mRNA is upregulated as early as 1 day after stroke and that protein production mainly occurs in the ischemic hemisphere by endothelial cells." (PMID 33058417, 2020). "RHP-treated mice maintained a 56 % increase in cortical CXCL13 protein at 2 days following stroke (P < 0.05)." (PMID 24485041, 2014). "One day after stroke induction, a >1.5-fold increase in CXCL13 protein was found in the ischemic cortex, with the magnitude of expression unaffected by prior RHP (both groups P < 0.0001 vs sham stroke)." (PMID 24485041, 2014). "CXCL13, a B cell-specific chemokine, was upregulated in post-stroke cortical vessels of both groups." (PMID 24485041, 2014). "We investigated the spatial and temporal expression of CXCL13 message and protein in the post-stroke brain." (PMID 24485041, 2014). "Immunohistochemistry revealed a predominantly vascular pattern of CXCL13 protein expression throughout the ischemic brain following stroke." (PMID 24485041, 2014). "To determine if RHP affected post-stroke CXCL13 protein expression, we also analyzed cortical lysates collected from the ischemic hemispheres to measure CXCL13 protein following stroke induction." (PMID 24485041, 2014). "By 2 days following stroke onset, cortical CXCL13 message was elevated in both untreated and RHP-treated groups (both P < 0.01)." (PMID 24485041, 2014). "Stroke induced a predominantly vascular expression of CXCL13 protein throughout the ischemic hemisphere, though others show both astrocytes and stimulated neurons can upregulate this chemokine during inflammation." (PMID 24485041, 2014). "With this data, we describe for the first time the expression pattern of the chemokine CXCL13 following stroke, and the novel maintenance of B cells in the protected ischemic cortex." (PMID 24485041, 2014). "Whether infiltrating monocytes/macrophages or dendritic cells also express CXCL13 and contribute to B cell infiltration in stroke remains to be determined." (PMID 33058417, 2020). "On the contrary, CXCL13, a B cell-specific chemokine, might participate in prevention of neurovascular protection from stroke." (PMID 27635404, 2016). "Our findings identified the upregulation of CXCL13 within the BBB in response to stroke." (PMID 24485041, 2014). "Therefore, it will be interesting to test whether alternate inhibitors of post-stroke acute inflammation with distinct mechanisms utilized in conjunction with anti-CXCL13 treatment could compound its beneficial effects." (PMID 35624463, 2022). "However, the expression of CXCL13 during CNS inflammation within the post-stroke ischemic cortex is unknown." (PMID 24485041, 2014). "One day after stroke induction, there was a 4-fold upregulation of CXCL13 mRNA in the cortex of RHP-treated mice compared to no-stroke values (P < 0.05)." (PMID 24485041, 2014). "As a result, there are also no studies investigating the post-stroke role of CXCL13, a chemokine that specifically recruits B cells during inflammation." (PMID 24485041, 2014). "Here, we show that CXCL13 is upregulated on inflamed vascular cells, and that during reperfusion, IL-21 producing CD4+ ICOS-1+ CXCR5+ TFH cells are recruited to the brain where they can induce caspase-mediated neuronal death and potentiate secondary stroke damage." (PMID 35624463, 2022).
Stroke (continued). "However, this early after stroke, endothelial‐derived CXCL13 may not be responsible for the delayed infiltration of ELS‐forming B cells." (PMID 33058417, 2020). "In the absence of stroke, RHP completed 2 weeks prior did not significantly affect baseline CXCL13 expression in either cortex or subcortex compared to untreated controls." (PMID 24485041, 2014).
angioimmunoblastic T-cell lymphoma (8 papers, 2008 to 2024). A mature T-cell non-Hodgkin lymphoma, characterized by systemic disease and a polymorphous infiltrate involving lymph nodes and extranodal sites. "CXCL13 has been proposed as a biomarker and is included in the diagnostic criteria for angioimmunoblastic T-cell lymphoma (AITL), an aggressive nodal T cell lymphoma." (PMID 36217194, 2022). "Gene expression profiling also allows better distinction of PTCL/NOS from angioimmunoblastic T cell lymphoma, the latter being characterised by follicular T helper lymphocyte derivation and CXCL13, PD1 and vascular endothelial growth factor expression." (PMID 18755717, 2008). "The gene expression profile also contributes to the better definition of the boundaries between PTCL/NOS and angioimmunoblastic T cell lymphoma, the latter deriving from follicular T helper lymphocytes and characteristically expressing CXCL13 and PD1 along with vascular endothelial growth factor." (PMID 18755717, 2008). "Angioimmunoblastic T-cell lymphoma (AITL) derives from T follicular helper cell expressing CXCL13, CD10 and PD-1 and has unique clinical and pathological features." (PMID 30150635, 2018). "On the other hand, most angioimmunoblastic T-cell lymphoma (AITL) cases express Tfh signature genes such as BCL6 in addition to PD-1 and CXCL13." (PMID 37788648, 2024). "For example, PTCL-NOS and angioimmunoblastic T-cell lymphoma (AITL) bear some similarities in terms of disease presentation, but PTCL-NOS is distinct from AITL in that AITL cells have solely a follicular T-helper phenotype (PD-1+, CXCL13+) and PTCL-NOS can include T-cells from differing subtypes." (PMID 27725924, 2016).
atherosclerosis (8 papers, 2015 to 2025). A disease characterized by the build-up of fatty material and calcium deposition in the arterial wall resulting in partial or complete occlusion of the arterial lumen. "We further profiled in the double-knockout NOD mice the cytokines and chemokines implicated in atherosclerosis, and found that CXCL13 and IL-1Ra were more induced on a HFD compared with normal diet." (PMID 30305306, 2018). "CXCR5 is the receptor for CXCL13, and both the deficiency of CXCR5 and CXCL13 have been shown to attenuate atherosclerosis, thus underscoring a clear role for CXCL13 signaling in atherosclerosis." (PMID 34948275, 2021). "In advanced atherosclerosis, activated LTo-like VSMCs highly expressed CXCL13 and CCL21 to induce ATLO neogenesis." (PMID 31921189, 2019). "Accumulating data demonstrated that CXCL13 and LTα1β2 might be the “bio-marker” predicting the formation of TLOs in some diseases, such as RA, SS, and atherosclerosis." (PMID 31921189, 2019). "It is known that lipid transport proteins (CAV-1, ABCA1, SREBP-1, LXR, etc.)and inflammation (HMGB1, CXCL13, TIMP-1, etc.)in blood vessels mediate the formation of atherosclerosis." (PMID 38622667, 2024). "QA inhibits the increase of cholesterol, TMA, TMAO, CXCL13, TIMP-1 and HMGB1 levels in peripheral blood of Apoe−/− mice induced by HFD, suggesting that QA can effectively inhibit HFD-induced atherosclerosis." (PMID 38622667, 2024). "Most importantly, these activated VSMCs themselves produce high levels of CXCL13 and CCL21, thus promoting TLO formation in adventitia in atherosclerosis." (PMID 31921189, 2019).